MC4R (melanocortin 4 receptor)
Diseases named in the same sentence as MC4R in open-access papers (continued):
Sharing a sentence is not in itself a finding about the gene and the disease.
Insulin resistance (55 papers, 2009 to 2025). Increased resistance towards insulin, that is, diminished effectiveness of insulin in reducing blood glucose levels. "MC4R deficiency in mice is associated with insulin resistance, renal sympathetic nerve activity inhibition and glucosuria elevation." (PMID 38448811, 2024). "Knockdown of central neural Kir2.1 from MC4R-deficient mice restored the insulin resistance of MC4R-deficient mice." (PMID 38448811, 2024). "We have identified central neural as a mechanism by which MC4R-deficient mice remain protected from energy imbalance and insulin resistance." (PMID 38448811, 2024). "Our results regarding carbohydrate metabolism confirm other studies linking this same MC4R polymorphism to insulin resistance." (PMID 37508717, 2023). "Transcripts with loss of function, such as Apom, Mc4r and Esr2 are strongly associated with glucose intolerance and/or insulin resistance." (PMID 32651395, 2020). "In the previous GWA study, the authors identified rs12970134 near MC4R associated with waist circumference and insulin resistance." (PMID 32390949, 2020). "Fasting glucose and lipid levels of the patients with MC4R mutation were normal, but insulin resistance was present in two of the subjects." (PMID 28218067, 2017). "MC4R (melanocortin 4 receptor) was identified by GWAS of a UK cohort of Indian-Asian and European ancestry as being associated with both insulin resistance, as measured by HOMA-IR and waist circumference, with higher risk-allele frequencies being found in the Indian-Asian cohort." (PMID 27312935, 2016). "Additionally, selective receptor re-expression in neurons of Mc4r knock-out mice normalized weight-loss and insulin resistance in mice after gastric bypass surgery." (PMID 24705671, 2014). "Association analysis for the relationship between validated SNPs in the explored candidate genes and quantitative variables of insulin resistance in PCOS with genetic effect sizes estimates derived for an additive genetic model (MC4R rs2229616 dominant genetic model) for the minor allele." (PMID 20092643, 2010). "Although this increment in Kir2.1 level is sufficient to cause reduced appetite and insulin resistance in MC4R-deficient mice, we speculate that hypothalamus-specific Kir2.1 knockout mice will exhibit significantly lower energy than that observed in MC4R-deficient mice." (PMID 38448811, 2024). "Specifically, we found that POMC neuronal activation is indispensable for energy homeostasis and insulin resistance triggered by MC4R knockdown-induced Kir2.1 activation in the state of HFD." (PMID 38448811, 2024). "Knockdown of Kir2.1 in POMC neuron-specific ablation of MC4R restored the effect of MC4R ablation on energy expenditure and systemic glucose homeostasis, indicating by reduced body weight and ameliorated insulin resistance." (PMID 38448811, 2024). "One possibility is that the MC4R gene is involved in regulating insulin resistance since animal studies revealed that MC4R knockout mice have 2-fold higher plasma insulin than their controls." (PMID 32733386, 2020). "This is probably because MC4R-KO mice fed WD exhibit morbid obesity with severe insulin resistance and hyperinsulinemia." (PMID 31969650, 2020). "The agouti-mice (Ay/a) have the increased expression of ASIP1, which antagonizes MC4R and provokes weight gain, fat deposition, glucose intolerance, the leptin and insulin resistance, and the impaired transport of leptin into the brain structures." (PMID 30870482, 2019). "The administration of high doses of AGRP and synthetic MC4R antagonists into healthy mice enhanced appetite and led to insulin resistance." (PMID 28031898, 2015). "Subsequent analyses showed that MC4R rs17782312, involved in weight regulation, and IRS1 rs2943634, related to insulin resistance were associated with MetS (OR 1.16, 95%CI 1.02-1.32 and OR 0.88, 95% CI 0.79; 0.97, respectively)." (PMID 23101478, 2012).
Insulin resistance (continued). "Therefore, insulin resistance may explain part of the association between MC4R rs17782313 and MetS." (PMID 23101478, 2012). "Individual SNPs for which we found an association with MetS were MC4R rs17782312 which is involved in weight regulation and IRS1 rs2943634 which is involved in insulin resistance." (PMID 23101478, 2012). "We then examined the effect of hypothalamic MC4R deletion on insulin resistance." (PMID 38448811, 2024). "MC4R-deficient mice develop insulin resistance without enhancement in beta cell function, and the improved glucose tolerance is attributed to glycosuria caused by reduced renal sympathetic nerve activity, similar to the mechanisms in POMC-deficient mice." (PMID 36210455, 2022). "Several studies suggest that MC4R regulates glucose homeostasis and insulin resistance, therefore, visfatin might be involved in this regulation but further studies are still required to understand the mechanism governing those MC4R functions." (PMID 32733386, 2020). "The loss of leptin signaling independent of the Mc4r pathway or the more pronounced hepatic insulin resistance in ob/ob mice may also affect the turnover of the TCA cycle." (PMID 37681411, 2023). "Both human and animal studies have suggested that the association between MC4R rs17782313 and MetS is at least partially independent of body weight, and, consequently, insulin resistance may mediate part of the relationship of MC4R rs17782313 with MetS." (PMID 36440355, 2022). "In summary, this study demonstrates that MC4R selectively in the ARC contributes to energy balance and insulin resistance by reducing the activation of POMC neuron via hypothalamus Kir2.1." (PMID 38448811, 2024). "It therefore suggests that suppression of de novo lipogenesis, probably due to improved glucose homeostasis and insulin resistance, also contributes to attenuate hepatic steatosis in CANA-treated MC4R-KO mice." (PMID 29402900, 2018). "Taken together, we speculate that MC4R-specific knockout in the arcuate nucleus upregulates Kir2.1 expression and inhibit POMC neuron activity, thereby increasing intake and insulin resistance in mice." (PMID 38448811, 2024). "In both human and animal studies MC4R rs17782313 had an effect on insulin resistance, independent of body weight." (PMID 23101478, 2012). "However, the mechanism by which MC4R in the arcuate nucleus (ARC) region regulates energy balance and insulin resistance remains unclear." (PMID 38448811, 2024). "However, the mechanism by which MC4R in the ARC region regulates energy balance and insulin resistance remains unclear." (PMID 38448811, 2024). "Deletion of the melanocortin 4 receptor (MC4R) in the DMV results in hyperinsulinemia and modest insulin resistance in a weight-independent manner and without changes in glucose tolerance or blood glucose levels." (PMID 32326226, 2020). "EPA treatment also reduced serum concentrations of TC, FFA, and ALT in MC4R-KO mice, whereas EPA treatment did not affect glucose metabolism and insulin resistance." (PMID 25816330, 2015).
diabetes (54 papers, 2011 to 2026). "The association of the MC4R gene polymorphism with overweight and the development of diabetes has been identified." (PMID 39605770, 2024). "In 2014, the association between polymorphism of the MC4R gene and overweight domestic shorthair cats with diabetes was investigated." (PMID 39605770, 2024). "We have now shown that hepatic FASN deficiency ameliorated NAFLD and diabetes in Mc4r-KO mice by suppressing DNL, FAO, and gluconeogenesis and improving hepatic insulin signaling without inducing hypertriglyceridemia." (PMID 37681411, 2023). "In our study, with adherence to diet therapy, C allele carriers and TT homozygotes of MC4R rs17782313 didn’t differ in body compositions changes, which is in agreement with the results of Diabetes Prevention Program (DPP)." (PMID 35292917, 2022). "A study in the framework within the Diabetes Prevention Program investigated 20 SNPs within the MC4R gene for association with weight loss in 3,000 individuals." (PMID 33801339, 2021). "This study suggests that the rs17782313 SNP in MC4R is related to diabetes and the SNP is also associated with cardiovascular disease in lean men." (PMID 32807123, 2020). "In our study for healthy subjects, the association of MC4R gene rs17782313 with diabetes was stronger in women than in men." (PMID 32807123, 2020). "The variant is located 576 kb downstream of MC4R, in close proximity to a region strongly associated with diabetes and related traits." (PMID 30453627, 2018). "In another study, a genetic analysis identified a missense mutation in the coding sequence of MC4R (MC4R:C.92 > T) related to diabetes mellitus in obese cats." (PMID 28629451, 2017). "The trend toward association detected for MC4R rs17782313, further analyzed by gender showed that women who had MC4R rs17782313 CT/CC genotype had higher prevalence of diabetes than those with TT allele." (PMID 23849767, 2013). "We examined whether the other two significant genes in the study, SLC30A8 and MC4R, associated with diabetes traits in our analysis." (PMID 34732801, 2021). "Collectively, these data indicate that the impairment of the counterregulatory responses in diabetes may be associated with the reduced hypothalamic Pomc and Mc4r expression." (PMID 30503832, 2019). "Therefore, enhancing MC4R function may minimize the risk of life-threatening hypoglycemia caused by insulin or its secretagogues during the treatment of diabetes." (PMID 30503832, 2019). "A role for arcuate nucleus neurons in FGF1-induced diabetes remission was strengthened further by evidence that functional melanocortin 4 receptor (MC4R)-signaling is required for this effect." (PMID 41371441, 2026). "The purpose of the study was to determine the prevalence of the melanocortin 4 receptor (MC4R) gene missense mutation among cats and to investigate the relationship between body condition score (BCS) and the occurrence of diabetes in felines." (PMID 39605770, 2024). "We identify monogenic diabetes variants in 2.4% of individuals and three exome-wide significant (P < 2.6 × 10−6) gene-level associations (HNF1A, MC4R, ATXN2L)." (PMID 38278947, 2024). "In this study, we investigated the relationship between diabetes, cardiovascular disease, and the rs17782313 MC4R SNP in Korean men and women." (PMID 32807123, 2020). "When analyzed by sex, the relationship between MC4R and diabetes was significant only for men (OR, 1.33; 95% CI, 1.04–1.70), not women (OR, 1.10; 95% CI, 0.70–1.75)." (PMID 32807123, 2020). "Overall, these data demonstrate the feasibility of using an MC4R agonist to defend against hypoglycemia in diabetes." (PMID 30503832, 2019). "For example, a few recent studies have employed Cre-LoxP technology to selectively reactivate MC4R expression in preganglionic vagal and sympathetic neurons and demonstrated the key role of this receptor in ameliorating diabetes in MC4R null mice." (PMID 23914153, 2013).
diabetes (continued). "Collectively, these findings suggested that hepatic FASN deficiency in Mc4r-KO mice suppresses FAO and gluconeogenesis in association with augmentation of insulin signaling, which together may ameliorate diabetes." (PMID 37681411, 2023). "Hepatic FASN deficiency thus ameliorated NAFLD and diabetes in melanocortin 4 receptor–deficient (Mc4r-KO) mice but not in mice fed a high-fat diet (HFD)." (PMID 37681411, 2023). "Hepatic FASN deficiency in Mc4r-KO mice ameliorates NAFLD and diabetes." (PMID 37681411, 2023). "There were no MC4R high confidence pLOF variants in our dataset and MC4R predicted damaging missense variants did not associate with diabetes-related traits in our study (all p > 0.19)." (PMID 34732801, 2021). "Our data exhibit that infusion of MSCs and its combination therapy with insulin might ameliorate diabetes signs by changing the amount of leptin and subsequent changes in the expression of neuropeptide Y and melanocortin-4 receptor." (PMID 32405365, 2020). "The relationship between diabetes and the MC4R gene SNP rs17782313 was examined." (PMID 32807123, 2020). "However, within the group of overweight cats with diabetes, 55% of animals were homozygous for the MC4R:c.92C allele, compared to 33% of lean cats with diabetes and 30% of non-diabetic cats." (PMID 39605770, 2024). "Such deficiency thus ameliorated NAFLD and diabetes in Mc4r-KO mice but not in HFD-fed mice." (PMID 37681411, 2023). "Therefore, we analyzed the association between diabetes and MC4R gene in the healthy subjects who did not have the cardiovascular disease." (PMID 32807123, 2020). "Therefore, enhancing MC4R function may improve hypoglycemia counterregulation in diabetes." (PMID 30503832, 2019). "Finally, we treated diabetic mice with the MC4R agonist MTII, administered stereotaxically into the PVH, to determine its potential for restoring the counterregulatory response to hypoglycemia in diabetes." (PMID 30503832, 2019). "We also measured Pomc and Mc4r mRNA levels in the ARC and PVH, respectively, in the streptozotocin-induced type 1 diabetes mouse model and non-obese diabetic (NOD) mice to delineate molecular mechanisms by which diabetes deteriorates the defense systems against hypoglycemia." (PMID 30503832, 2019). "Given the reduced Mc4r expression in the STZ treated mice, we hypothesized that enhancing MC4R signaling via MTII administration may improve the counterregulatory response to insulin induced hypoglycemia in diabetes." (PMID 30503832, 2019). "MC4R knockout (KO) rats are obese and profoundly insulin resistant without frank diabetes." (PMID 24400148, 2013).
metabolic syndrome (51 papers, 2010 to 2025). A cluster of metabolic risk factors for CARDIOVASCULAR DISEASES and TYPE 2 DIABETES MELLITUS. "Our observations were in line with earlier evidence that revealed a significant association between near MC4R rs17782313 and metabolic syndrome." (PMID 36440355, 2022). "As previously shown by us and other groups, Mc4r deficiency leads to the metabolic syndrome accompanied by significantly increased body weight, hyperlipidemia and hepatic steatosis." (PMID 28207798, 2017). "Existing models of Mc4r null-mutant mice and rats as well as mice with a partial loss-function mutation both develop the symptoms of the metabolic syndrome including significantly increased body weight, hyperlipidemia and hepatic steatosis." (PMID 28207798, 2017). "Variants in and near MC4R have been linked to metabolic syndrome, percent body fat, eating behavior, higher fat intake, and lower energy expenditure." (PMID 26537541, 2015). "Meta-analyses between the MC4R rs17782313 polymorphism and dyslipidemia indexes." (PMID 37621650, 2023). "PheWAS of extreme rare variants (MAF < 0.1%), using burden test methodology, provided an initial exploratory association of the MC4R coding variants with abnormal glucose test, presence of casts in urine, dysmetabolic syndrome X, pituitary hypofunction, and neurofibromatosis." (PMID 32952152, 2021). "Voluntary wheel running in obese rats is reported to attenuate the metabolic syndrome in MC4R deficient rats with dopamine dysregulation even though the reward signals are blunted; MC4R are highly expressed by dopamine secreting neurons in the mesolimbic dopamine pathway." (PMID 29867590, 2018). "Results from this study revealed that carriers of the rare allele in the MC4R gene and having the highest score of the western dietary pattern had increased risk (odds ratio—OR) of developing metabolic syndrome (OR = 1.71 (1.04–2.41); Ptrend = 0.007), as compared to those having lower scores." (PMID 28829397, 2017). "Thus, we used mouse models with a partial loss-of-function mutation in the Mc4r which mimics mutations found in humans and consequently lead to the development of the Mc4r-associated symptoms of the metabolic syndrome including NAFLD." (PMID 28207798, 2017). "Furthermore, NAFLD is the main hepatic manifestation of the metabolic syndrome, often accompanied by alterations in glucose homeostasis and waist circumference, and has been directly associated with genetic variations of Mc4r." (PMID 28930194, 2017). "No BS for either KLF14 or SREBF1 was identified in the promoters of MC4R, 5-HT2C, MC3R, S1PR2, FFAR1/GPR40, and HCR2 within this database, despite their known association with metabolic syndrome." (PMID 40243421, 2025). "The adult-onset metabolic syndrome in Avy/a mice is thought to be mediated at least in part by the agouti protein acting as an inverse agonist at the Mc4r, which plays an important role in feeding inhibition." (PMID 24289264, 2013). "Neuroendocrine dysfunction, particularly involving the MC4R pathway, may also impair metabolic homeostasis, leading to dyslipidemia and an increased propensity for hepatic steatosis." (PMID 40443456, 2025). "If stored cord blood was available, the methylation levels of proopiomelanocortin (POMC), the melanocortin 4 receptor (MC4R), and hepatocyte nuclear factor 4 alpha (HNF4a; associated with metabolic syndrome) were assayed in participants in check-up examinations at the ages of 7-9 years." (PMID 33677859, 2021). "Since hypertension is one of the most frequent components of metabolic syndrome, its absence could also influence the prevalence of whole metabolic syndrome in SIM1 and MC4R mutation carriers." (PMID 28472148, 2017). "However, when analyzed separated, neither MC4R nor FTO were associated with any individual metabolic syndrome feature, including waist circumference." (PMID 23849767, 2013).
metabolic syndrome (continued). "Here, MetS-Z-BMI scores, a continuous measure based on body mass index (BMI), were calculated to determine metabolic syndrome severity and response to treatment with the melanocortin-4 receptor agonist setmelanotide in BBS." (PMID 39919037, 2025). "The metabolic syndrome of asip overexpression is mediated by Mc4r, given that Asip can also antagonise MSH binding at Mc4r and depress the constitutive activity of Mc4r as an inverse agonist." (PMID 37237525, 2023). "Among the genes with the strongest relationship with metabolic syndrome, CNR1—cannabinoid receptor 1 gene, LEP—leptin promoter gene, FTO—alpha-ketoglutarate-dependent dioxygenase gene, MC4R—melanocortin 4 receptor gene and VDR—vitamin D receptor stand out." (PMID 32272684, 2020). "Methylation studies of the MC4R gene indicate a connection to metabolic syndrome, yet show no direct link to obesity." (PMID 41423640, 2025). "The impact of MC4R on sexual behavior appears to be independent of its impact on body weight, offering hope that drug therapies to treat metabolic syndrome in women can avoid triggering alterations in their sexual experiences." (PMID 37033219, 2023). "Abnormal glucose test (N = 33), colonic polyps (N = 29), dysmetabolic syndrome X (N = 11), and urinary cast (N = 10) were among the most frequent traits among MC4R carriers that while suggestive, did not achieve significance (P < 0.001)." (PMID 32952152, 2021). "This metabolic syndrome is mediated by antagonizing α-MSH signaling at central MC4R that arbitrates the negative effects of melanocortin peptides on the energy balance." (PMID 23251332, 2012). "The additional risk associated with possessing several SNPs, particularly when integrating FTO, MC4R, and FABP2, increases the likelihood of developing metabolic syndrome, even in the absence of observable symptoms." (PMID 41226372, 2025). "It appeared that the effect sizes of most T2D-associated SNPs, with the exception of a few outliers (e.g., FTO, MC4R, POCS, and TFAP2B), were not affected by BMI or dyslipidemia." (PMID 30054458, 2018).